TRPC6 (transient receptor potential cation channel subfamily C member 6)
Diseases named in the same sentence as TRPC6 in open-access papers (continued):
Sharing a sentence is not in itself a finding about the gene and the disease.
Alzheimer disease (16 papers, 2020 to 2025). A progressive, neurodegenerative disease characterized by loss of function and death of nerve cells in several areas of the brain leading to loss of cognitive function such as memory and language. "In fact, dysregulation of TRPC6 activity has been found to cause many neurobiological disorders, including Alzheimer's disease, autism spectrum disorders, and depression." (PMID 40994415, 2025). "Previously, an inhibitory effect of presenilin 2 and its Alzheimer’s-disease-linked variants on receptor-operated TRPC6 function has been demonstrated in heterologous expression systems, suggesting functional interaction between presenilins and TRPC6." (PMID 33490083, 2020). "We suggest that C20 might be recognized as the novel TRPC6-selective drug suitable to treat synaptic deficiency in Alzheimer’s disease-affected hippocampal neurons." (PMID 36362339, 2022). "Increasing TRPC6 activity by the TRPC6 agonist (hyperforin) dramatically reduced Aβ levels which were a major pathological factor for Alzheimer’s disease and ameliorated cognitive performance." (PMID 35875795, 2022). "The dysregulation of TRPC6 has been reported to be involved in the pathophysiology of several neurodegenerative diseases such as Alzheimer’s disease, cerebral ischemia, epilepsy, depression, and so on." (PMID 35875795, 2022). "Significantly reduced TRPC6 mRNA levels in the blood cells were found in patients with Alzheimer’s disease compared to that age-matched controls." (PMID 35875795, 2022). "Several studies demonstrated that the selective TRPC6 activator hyperforin reduces Aβ levels and improves behavioral performance in Alzheimer’s disease (AD) animal models and in vitro studies." (PMID 36224261, 2022). "In fact, TRPC6 channels have been studied as an emerging area of research as a molecular target for neuroprotective agents in Alzheimer’s disease and cerebral ischemia." (PMID 34327201, 2021). "Existing studies have shown that cognitive impairment is the most common and challenging syndrome in clinical practice in Alzheimer’s disease, and that blood cell TRPC6 mRNA levels are reduced in patients with Alzheimer’s disease and mild cognitive impairment." (PMID 34327201, 2021). "TRPC6 also regulates several beneficial processes in the neurons such as survival, synaptogenesis, learning and memory, all of which are altered in Alzheimer’s Disease." (PMID 33240883, 2020). "The present review summarizes current knowledge on the role of TRPC6 channels in the development of two neurological disorders: Alzheimer’s disease and cerebral ischemia." (PMID 33114455, 2020). "Importantly, loss of TRPC6 expression leads to the activation of Rac1 in the kidney, which suggests that the lower expression of this channel observed in the brain of Alzheimer’s-disease patients could also promote the pathology by activating Rac1." (PMID 33240883, 2020). "For example, a system wide reduction of TRPC6 expression was found in patients with Alzheimer’s disease and mild cognitive impairment, including blood cells, which negatively correlated with the cognitive performance." (PMID 33490083, 2020). "Downregulation as well as upregulation of TRPC6 channel functions have been observed in Alzheimer’s disease and brain ischemia models." (PMID 33114455, 2020). "Transient receptor potential canonical channel 6 (TRPC6) is a potential therapeutic target for Alzheimer's disease (AD) and its expression is highly regulated by glucose concentration." (PMID 33135341, 2020). "The piperazine derivative N-(2,6-difluorophenyl)-2-(4-phenylpiperazin-1-yl)propanamide (cmp2) has emerged as a potential transient receptor potential cation channel, subfamily C, member 6 (TRPC6) modulator, offering a promising pathway for Alzheimer’s disease (AD) therapy." (PMID 40429735, 2025).
Alzheimer disease (continued). "For example, it was found that TRPC6 in the blood was significantly suppressed in patients with mild cognitive impairment and could be used as a potential indicator for PD or Alzheimer's disease." (PMID 33325158, 2021). "Also, pharmacological activation of TRPC6 inhibited the elevation of Aβ and phospho-tau in neurons of patients, indicating a possible protective role of TRPC6 in Alzheimer’s-disease." (PMID 33240883, 2020). "Thus, in order to protect neurons from Alzheimer’s disease and cerebral ischemia, proper TRPC6 channels modulators have to be used." (PMID 33114455, 2020). "Moreover, TRPC6 expression and activity are diminished in neurons from Alzheimer’s-disease patients." (PMID 33240883, 2020). "Moreover, neurons differentiated from induced pluripotent stem cells (iPSCs) derived from peripheral blood of sporadic Alzheimer’s disease patients also exhibit decreased TRPC6 expression, as well as elevated Aβ and phosphorylated tau levels, hallmarks of Alzheimer’s disease." (PMID 33490083, 2020). "This review summarizes the currently available information about potential drug candidates that may be used as basic structures to develop selective, highly potent TRPC6 channel modulators to treat neurodegenerative disorders, such as Alzheimer’s disease and cerebral ischemia." (PMID 33114455, 2020). "Though many aspects of the physiology and regulation of TRPC6 are still elusive, dysfunction of the TRPC6 channel may trigger a wide range of CNS-related diseases such as epilepsy, autism spectrum disorder (ASD) and Alzheimer’s disease, characterized by cognitive dysfunction." (PMID 34327201, 2021). "The beneficial effect of TRPC6 to Alzheimer’s disease was demonstrated by showing that stimulating TRPC6 or the store-operated Ca2+ entry improved hippocampal long-term potentiation of the APP-presenilin 1 mutant mice, an experimental model of Alzheimer’s disease." (PMID 33490083, 2020).
ischemia (16 papers, 2017 to 2025). A hypoperfusion of the BLOOD through an organ or tissue caused by a PATHOLOGIC CONSTRICTION or obstruction of its BLOOD VESSELS, or an absence of BLOOD CIRCULATION. "The human TRPC6 is a 931 residues cation transport channel associated with smooth muscle contraction, pulmonary endothelial permeability, neuronal protection against ischemia, and podocytes’ structure and function." (PMID 34288970, 2021). "Transgenic mice overexpressing TRPC6 demonstrate enhanced motor performance following ischemia in the rotarod test." (PMID 40429735, 2025). "It is reported that activating TRPC6 in a rat model of cerebral ischemia was shown to prevent neuronal death, whereas blocking TRPC6 enhanced sensitivity to ischemia." (PMID 33669830, 2021). "Activating TRPC6 in various cerebral ischemia models has been found to prevent neuronal death, whereas blocking TRPC6 enhances sensitivity to ischemia." (PMID 33669830, 2021). "It has been reported that downregulation or inhibition of TRPC6 during ischemia contributes to brain damage in rodent models, and upregulation or activation by hyperforin and resveratrol attenuates this damage." (PMID 32963700, 2020). "For example, in a transient model of middle cerebral artery occlusion (tMCAO), TRPC6 protein levels in neurons are found to be greatly reduced in ischemia as a result of NMDA receptor-dependent calpain proteolysis." (PMID 32963700, 2020). "Overexpression of TRPC6 inhibits [Ca2+]i overload, prevents neuronal death, lessen infarct size, and improves behavior performance after ischemia." (PMID 33604333, 2020). "Although the present study showed a protective role of the TRPC6 channel in astrocytes after ischemia, various questions remain unanswered." (PMID 33604333, 2020). "In parallel, overexpression of TRPC6 also decreased IR injury-induced astrocytic apoptosis, cytotoxicity, inflammatory responses and NF-κB phosphorylation in modeled ischemia in vitro." (PMID 33604333, 2020). "Overexpression of astrocytic TRPC6 also attenuated apoptosis, cytotoxicity, inflammatory responses, and NF-κB phosphorylation in modeled ischemia in astrocytes." (PMID 33604333, 2020). "Q-PCR and Western Blot further showed that the mRNA and protein expressions of Synaptopodin, Nephrin, and CD2AP decreased by ischemia in a time-dependent manner, while the expression of TRPC6 mRNA and protein increased in a time-dependent manner." (PMID 30922260, 2019). "To elucidate why the contractility was even higher in the nimodipine groups, we investigated if the 48 hours nimodipine treatments resulted in increased expression of TRPC6 which has been shown to be important in other models of ischemia." (PMID 30978262, 2019). "Different from the present findings, however, activation of TRPC6 before ischemia has been reported to have neuroprotective effects on retinal ganglion cells." (PMID 28400714, 2017). "Furthermore, “calycosin”, a major isoflavonoid in Radix Astragali Mongolici, protected against ischemia-induced damage by inhibiting calpain activation and increasing TRPC6 and p-CREB levels." (PMID 33669830, 2021). "Activation of TRPC6 in VSMCs of the cerebral vasculature might contribute to the no-reflow phenomena and attenuation of metabolic vasodilation in ischemia." (PMID 33669830, 2021). "The predominant constituent of green tea, (-)-epigallocatechin-3-gallate (EGCG), introduced immediately after ischemia, demonstrates neuroprotection by decreasing calpain activity and activating TRPC6/CREB via the mitogen-activated protein kinase (MEK)/extracellular pathway." (PMID 33669830, 2021). "Inhibiting TRPC6 degradation prevents ischemic brain damage, with a reduction in infarct volume at 24 hours after reperfusion, an improvement in behavior performance, and a lower mortality within 35 days after ischemia." (PMID 32963700, 2020). "In general, TRPC6 attenuates astrocytes IR injury in modeled ischemia in vitro." (PMID 33604333, 2020).
ischemia (continued). "Animal models in which TRPC6 expression had been silenced revealed that TRPC6-mediated cellular responses prevented necroptosis of renal tubular epithelial cells, suggesting that TRPC6 contributes to protect the kidney from ischemia-reperfusion injury." (PMID 29973568, 2018). "Thus, deletion of TRPC6 would be expected to reduce ischemia-induced brain damage and OGD-/glutamate-induced cortical cell death." (PMID 28400714, 2017). "Thus, enhancing EDH activity by inhibiting TRPC6 channel activity in VSMCs may be critical for capillary arterialization followed by blood flow recovery after hindlimb ischaemia." (PMID 36068079, 2023). "Existing controversies regarding the TRPC6 function in the development of brain ischemia might be due to different experimental settings (i.e., rodent model, sex, age, the method used to model ischemia)." (PMID 33114455, 2020). "TRPC6 and other TRPCs can be activated by phospholipase C (PLC) by numerous stimulations, such as inflammation and ischemia-reperfusion (IR) injury." (PMID 33669830, 2021). "Our study has demonstrated that TRPC6-mediated Ca2+ influx enhanced excitotoxicity by facilitation of NMDAR activation and TRPC6 deletion attenuated ischemia-induced neuronal death." (PMID 28400714, 2017). "Overexpression of TRPC6 in bone marrow stromal cells via a CRISPR-based synergistic activation mediator could decrease brain injury significantly and improve neurofunctional outcomes in a rat model of ischemia/reperfusion." (PMID 35875795, 2022). "Hence, TRPC6 ablation does not affect rCBF before, during, or after ischemia." (PMID 28400714, 2017).
nephrotic syndrome (16 papers, 2013 to 2025). A collection of symptoms that include severe edema, proteinuria, and hypoalbuminemia; it is indicative of renal dysfunction. "Abnormal function of canonical transient receptor potential‐6 channels (TRPC6) has been implicated in the pathogenesis of familial and acquired forms of severe nephrotic syndromes." (PMID 41165237, 2025). "Since those initial reports, many other TRPC6 mutations have been identified in patients with nephrotic syndromes." (PMID 36421724, 2022). "Familial nephrotic syndromes are quite rare, and only a small proportion of the familial forms are due to mutations in TRPC6." (PMID 36421724, 2022). "Note that the overall abundance of podocin in the cell layer was unchanged following 24‐h activation of TRPC6, in marked contrast to what is observed following 24 h exposure to sera from patients with recurrent nephrotic syndromes." (PMID 41165237, 2025). "Sporadic TRPC6-AP demonstrated an earlier progression to KF than familial cases (P = .001) and were more likely to present with nephrotic syndrome [odds ratio 4.34 (1.85-10.15); P = .001]." (PMID 40388293, 2025). "This further underpins a role for TRPC6 in the pathogenesis of nephrotic syndrome." (PMID 39946431, 2025). "The identification of the two Ca2+ permeant channels TRPC5 and TRPC6 as mediators of this pathway not only bolstered the importance of podocyte cytoskeleton dynamics but also revealed promising drug targets for treatment-resistant nephrotic syndrome." (PMID 26490951, 2016). "The commonest genes associated with nephrotic syndrome differ at birth (NPHS1, NPHS2, WT1, LAMB2, PAX2, PLCE1), in childhood or adolescence (NPHS1, NPHS2, WT1, LAMB2, SMARCAL1, NUP107, TRPC6, PLCE1) and in adults (COL4A3-COL4A5, GLA, ACTN4, CD2AP, INF2, TRPC6)." (PMID 37578539, 2024). "Interestingly, more recent reports show that TRPC6 activity is linked to increased calpain 1 and calcineurin activity contributing to PAN-induced podocyte injury as well as promoting the pathogenesis of nephrotic syndrome and podocyte injury." (PMID 37615749, 2023). "This study is aimed at exploring the mechanism by which the −254C>G single nucleotide polymorphism (SNP) on the transient receptor potential cation channel 6 (TRPC6) gene promoter could increase its activation in steroid-resistant nephrotic syndrome children of China." (PMID 31281825, 2019). "However, the controversy among results of studies on gene mutation analysis on steroid resistant nephrotic syndrome does not undermine the significant role of TRPC6 gene mutations in producing podocytopathy and steroid resistant nephritic syndrome." (PMID 28197479, 2015).
heart failure (15 papers, 2017 to 2025). Inability of the heart to pump blood at an adequate rate to meet tissue metabolic requirements. "Relating thereto, a study recently demonstrated an association between elevated TRPC6 expression and a higher risk of heart failure after chemotherapy with the cardiotoxic drug doxorubicin." (PMID 41118703, 2025). "Hypertrophic cardiomyopathy and cardiac failure are caused by the overexpression of TRPC6, and the inhibition of its expression ameliorates cardiac fibrosis and myocardial ischemia–reperfusion injury." (PMID 39863867, 2025). "The TRPC family of proteins (TRPC1-7) function as both homo- and hetero-tetramers, and both Trpc1 and Trpc3 as well as Trpc6 have been implicated in heart failure induced by pressure overload." (PMID 35096991, 2021). "We first investigated whether deletion of TRPC6 also attenuates pressure overload-induced heart failure using TRPC6-deficient (TRPC6(−/−)) mice." (PMID 28790356, 2017). "Additionally, an observational study (NCT05507879) is currently exploring whether TRPC6 variants can predict chemotherapy-related cardiomyopathy and heart failure in breast cancer patients." (PMID 41118703, 2025). "Upregulation of TRPC3, TRPC6, and TRPP2 has also been associated with myocardialremodeling, which contributes to cardiomyocyte hypertrophy and accelerates theprogression of heart failure." (PMID 40630446, 2025). "In heart failure models, TRPC6 upregulation has been observedto enhance contractility in cardiomyocytes, though it also leads to electricalinstability." (PMID 40630446, 2025). "In the heart, TRPC6-mediated zinc influx enhances myocardial contractility, suggesting its potential as a therapeutic target for heart failure." (PMID 41118703, 2025). "Here we show that the knockout of transient receptor potential canonical (TRPC) channel isoforms TRPC1 and TRPC6 can ameliorate LPS-challenged heart failure and prolong survival in mice." (PMID 36460692, 2022). "Second, animal studies have demonstrated that overexpression of Trpc6 leads to hypertrophic cardiomyopathy and heart failure in mice and genetic deletion or inhibition of Trpc6 reduces pressure overload in models of HF." (PMID 32903434, 2020). "Two loci, TRPC6 and CBR3, were associated with cardiac events in the NSABP B-31 patients and analyses suggest that both associations are the effects of chemotherapy rather than trastuzumab and further extend the evidence for both as putative risk genes for doxorubicin-induced heart failure." (PMID 37305569, 2023). "Downstream of TRPC6, cardiomyocyte specific overexpression of an active-CALCINEURIN isoform in adult mice is sufficient to trigger pathological hypertrophy and heart failure." (PMID 38259319, 2023). "However, whether TRPC6 inhibition is sufficient to improve heart failure is still obscure." (PMID 28790356, 2017). "Mechanotransduction and Heart Failure: Mechanosensitive TRP channels (e.g., TRPC6, TRPM7, TRPV4) are activated under pathological stretch, making them promising targets in heart failure." (PMID 40313873, 2025). "Elucidation of the role of TRPC6 as an endogenous negative regulator of ROS signaling deepens the understanding of the molecular diversity and function of TRPC channels and will provide a novel therapeutic strategy for heart failure." (PMID 28790356, 2017). "As the inhibition of TRPC3, but not TRPC6, actually suppressed pressure overload-induced heart failure, oxidative modification of Gpx3 will be a novel biomarker for diagnosing the severity of maladaptive cardiac remodeling." (PMID 28790356, 2017). "In this study, we demonstrate that deletion of TRPC6 failed to suppress pressure overload-induced heart failure as well as oxidative stress, despite significant attenuation of cardiac fibrosis in mice." (PMID 28790356, 2017). "We here demonstrated that deletion of TRPC6 had no impact on pressure overload-induced heart failure despite inhibiting interstitial fibrosis in mice." (PMID 28790356, 2017).
heart failure (continued). "This implies that the beneficial positive inotropic effect by TRPC6 activator is not expected in heart failure patients treated with β-blockers, but TRPC6-mediated Zn2+ influx may help reduce the load on the heart." (PMID 36289215, 2022). "Interestingly, significant overexpression of TRPC1/C3/C4/C5 or TRPC6 was detected in patients with heart failure as compared to nonfailing heart." (PMID 30881310, 2019).